GPX4 (glutathione peroxidase 4)
Diseases named in the same sentence as GPX4 in open-access papers (continued):
Sharing a sentence is not in itself a finding about the gene and the disease.
tumor (continued). "For example, scalarane-type sesquiterpenes isolated from sponges were found to induce elevated levels of lipid peroxidation in tumor cells by inhibiting GPX4 protein stability, thereby selectively triggering ferroptosis." (PMID 40559667, 2025). "ROS accumulation resulting from GPx4 downregulation has been shown to enhance anti-tumor immune response and reshape tumor microenvironment by reducing lactic acid." (PMID 39908861, 2025). "High SLC7A11 expression promotes GSH synthesis by mediating cystine transport, upregulating GPX4 activity, enhancing the antioxidant capacity of tumor cells, scavenging ROS, and inhibiting ferroptosiss." (PMID 40084254, 2025). "As a critical regulator of ferroptosis in tumors, GPX4 not only modulates tumor growth but also impacts tumor immune microenvironment." (PMID 40365295, 2025). "By employing preclinical models of TNBC, we demonstrate that defense against lipid oxidative stress is critical in TNBC tumor metabolism and survival through the antioxidant enzyme GPX4." (PMID 40001204, 2025). "The western blot results of protein extraction after tumor milling also indicated that the expression of GPX4, SLC7A11, and FADS2 proteins was decreased in the UA group." (PMID 40535804, 2025). "The inhibition of key ferroptosis regulators, such as glutathione peroxidase 4 (GPX4), promotes selective cancer cell death in vitro and prevents tumor recurrence in vivo." (PMID 40427052, 2025). "In mice inoculated with either HCT116‐WT or HCT116‐PRDX5 O.E. cells, okanin injection i.p. downregulated the protein levels of both PRDX5 and GPX4 in all tumor tissues." (PMID 40831323, 2025). "EBV infection induces GPX4 stabilization via p62–Keap1–Nrf2 signaling, promoting chemoresistance and tumor progression." (PMID 41373599, 2025). "Inducers of ferroptosis, such as erastin (which inhibits system Xc- transporter) and RSL3 (which directly inhibits GPX4), can trigger tumor cell death in metabolically vulnerable cancers." (PMID 41562065, 2025). "Research indicates that pharmacological interventions can block the activation of the Nrf2/GPX4 signaling pathway, thereby enhancing the sensitivity of tumor cells to ferroptosis." (PMID 40599237, 2025). "Fin56, a newly identified type III ferroptosis inducer, directly promotes the degradation of GPX4 exhibiting potent anti-tumor effects." (PMID 41301848, 2025). "In this context, we explored the link between GPX4 expression and the infiltration of immune cells in tumor tissues." (PMID 41142608, 2025). "GPX4 also influences the tumor microenvironment by affecting immune responses and angiogenesis, thus modulating tumor growth." (PMID 40599237, 2025). "Ferroptosis in tumor cells is alsoinduced by compounds that block GPX4 activity (e.g., altretamine, anFDA-approved alkylating agent)." (PMID 40264585, 2025). "Tumor cells with high ZEB1 expression exhibit heightened dependence on GPX4, as GPX4 counteracts the oxidative effects of intracellular peroxides on PUFAs in cellular membranes, thereby attenuating ferroptosis." (PMID 40709182, 2025). "Correlatives: serial stool metagenomics/metabolomics, tumor biopsies for SLC7A11/GPX4/FSP1 expression and BODIPY lipid peroxidation assays, and peripheral immune phenotyping." (PMID 41301464, 2025). "Additional functional assays indicated that GPX4 expression in GC cells affected macrophage-mediated tumor cell killing through changes in conditioned media." (PMID 40365295, 2025).
tumor (continued). "TRIM36, a novel androgen-responsive gene, has been shown to regulate tumor plasticity in neuroendocrine prostate cancer (NEPC) by repressing glutathione peroxidase 4 (GPx4) expression in a manner dependent on HK2 ubiquitination." (PMID 40771930, 2025). "The initial phase of the study concentrated on the GPX4 expression profile across various cancerous tissues, revealing that GPX4 expression was significantly higher in tumor tissues than in normal tissues for the majority of cancers examined." (PMID 41142608, 2025). "Studies have indicated that CD8+ T cells exhibit greater ferroptosis sensitivity than tumor cells, especially under GPX4 inhibition." (PMID 40892295, 2025). "In the highly mesenchymal state, tumor cell relies on GPX4 to live, they also have higher sensitivity with GPX4 inhibitors." (PMID 40855044, 2025). "Specific tumor cells demonstrate resistance to ferroptosis by enhancing antioxidant mechanisms, including glutathione peroxidase 4 (GPX4), to counteract lipid peroxides." (PMID 40710325, 2025). "In radioresistant tumor cells, CoQ upregulation shifts ferroptosis inhibition from GPX4 to FSP1, promoting radiotherapy resistance." (PMID 39935430, 2025). "Dysregulation of these RNA networks in HNSCC correlates with tumor progression and resistance to GPX4 inhibitors." (PMID 40650229, 2025). "Immunohistochemical analysis of tumor tissue from the xenograft model similarly revealed weaker GPX4 staining in BMN673-treated SK-CO-1 groups compared to controls." (PMID 41266732, 2025). "In parallel, dEGCG cooperates with tumor-infiltrating lymphocyte (TIL)-derived IFN-γ to potentiate ferroptosis by suppressing GPX4 and inhibiting system x_c−, leading to sustained lipid-peroxide accumulation and regulated cell death." (PMID 41209565, 2025). "In this study, we observed a significant decrease in kynurenine levels following GPx4 knockdown in tumor cells via metabolomic analysis." (PMID 40365295, 2025). "Research indicates that GPX4 is more abundantly expressed in tumor cells than in normal cells, which correlates with increased levels of H3K4me3 on the GPX4 promoter." (PMID 40327848, 2025). "One of the most clinically relevant antioxidant enzymes in cancer is GPX4, which protects tumor cells from ferroptosis by reducing lipid hydroperoxides in a glutathione-dependent manner." (PMID 40867898, 2025). "As for ferroptosis markers, RACGAP1 silencing markedly reduced the expression of GPX4, while increased the tumor tissue iron content, serum iron content and serum peroxidation MDA level." (PMID 41444950, 2025). "Recent studies have highlighted the importance of GPX4 in cancer cell survival, drug resistance and tumour progression." (PMID 40576169, 2025). "Immunohistochemistry analysis showed significant downregulation GPX4 expression in the Cu2O@EG + MW group after 18 days, weakening the tumor's antioxidant system and promoting ferroptosis." (PMID 40789052, 2025). "The ferroptosis inhibitor GPX4 showed subtype-dependent regulation in PDTC of NSCLC ex vivo correlating with the tumor apoptotic fraction." (PMID 40436830, 2025). "Suppresses tumor growth by inducing ferroptosis marked by GPX4 downregulation and lipid peroxidation." (PMID 41008615, 2025). "In drug development, novel inducers like compound 26a (targeting GPX4) show strong anti-tumor activity, while inhibitors such as 2-vinyl-10H-phenothiazine derivatives reduce toxicity without sacrificing efficacy." (PMID 40143112, 2025). "GPX4 plays a pivotal role in regulating the ferroptosis process and has the potential to affect tumor growth by modulating ROS levels." (PMID 39917169, 2025). "Its combination with the GPX4 inhibitor ML210 further enhances its anti-tumor effects, presenting a potential therapeutic target for OCCC." (PMID 40539051, 2025). "Targeting GPX4 to induce ferroptosis is a promising strategy for overcoming acquired drug resistance, as persister tumor cells rely on GPX4 for survival." (PMID 40424719, 2025).
tumor (continued). "Examples include tumor-homing liposomes that co-deliver GPX4 inhibitors plus PD-L1 antibodies, iron oxide nanoparticles that catalyze Fenton reactions locally, and hydrogel matrices for rectal/topical delivery in localized disease." (PMID 41301464, 2025). "In vivo, CMP significantly inhibited the growth of OC xenografts and reduced the expression levels of Nrf2, HO-1, xCT and GPX4 in tumor tissues." (PMID 40539051, 2025). "Intracellular GSH and GPX4 as important antioxidant defenses to protect tumor cells from ferroptosis were measured." (PMID 40367177, 2025). "In turn, activation of GPX4 prevents lipid peroxidation and ferroptosis while inhibiting tumor growth." (PMID 40070574, 2025). "The results showed that in-016975/Sora@PLGA-CM boosted the sensitivity of orthotopic HCC to sorafenib and effectively suppress tumor progression by inducing hsa_piR_016975/Maspin/GPX4 axis-mediated ferroptosis." (PMID 40606680, 2025). "Knockdown of SQLE significantly increased the sensitivity of OC cells to ferroptosis inducers, such as GPX4 inhibitors, and markedly inhibited tumor growth in in vivo experiments." (PMID 40539051, 2025). "Further experiments showed that Gpx4 knockout suppressed tumor growth, slowed proliferation, increased cell death, and prevented distant metastases in vivo." (PMID 40861444, 2025). "Inhibition of SLC7A11 or GPX4 with ferroptosis inducers can increase the sensitivity of radioresistant tumor cells and xenografts to radiotherapy." (PMID 41293165, 2025). "In fact, androgen receptor (AR) inhibitors strongly reduce GPX4 expression, demonstrating that AR promotes and drives GPX4 expression in LAR subtype of TNBC tumor." (PMID 41339932, 2025). "Of note, we demonstrate that ALDH3A2 suppresses the proliferation, migration, and invasion of GC cells by promoting ferroptosis in a GPX4-dependent manner, thereby suppressing aggressive tumor progression." (PMID 41444219, 2025). "DNA methylation induces ferroptosis in tumor cells by regulating GPX4, a key molecule in ferroptosis." (PMID 40959280, 2025). "This targeted inhibition effectively impedes the cellular uptake and influx of extracellular Cys2, thereby indirectly suppressing GPX4 enzymatic activity and ultimately leading to the highly efficient induction of ferroptosis in tumor cells." (PMID 41339932, 2025). "Previously, targeted monotherapy‐resistant cancer cells were more sensitive to the GPX4 inhibitors as they induce ferroptotic cell death in many cancer cell lines in various tumor tissues in vitro." (PMID 39369284, 2025). "Several studies have indicated that GPX4 exhibits a dual role in human cancers, possessing both tumor-suppressive and oncogenic properties." (PMID 41142608, 2025). "Emerging evidence suggests that β-catenin and GPX4 cooperatively regulate tumor progression and chemotherapy response through ferroptosis modulation." (PMID 40768425, 2025). "Univariate analysis revealed that GPx4 expression (P = 0.007), tumor location (P < 0.001), T stage (P = 0.001), N stage (P = 0.001), M stage (P < 0.001), and TNM stage (P < 0.001) as prognostic risk factors for GC patients." (PMID 39908861, 2025). "The transferred tumor-infiltrating OT-I GPX4–/– CD8+ T cell population was significantly reduced compared with WT counterpart in tumor accumulation and lost their ability to proliferate and produce IFN-γ, especially with α4-1BB treatment." (PMID 40178905, 2025). "GPX4 inhibition using RSL3 is a successful anti-tumor agent in vitro, but its limited bioavailability makes it challenging to use in vivo." (PMID 40957885, 2025). "A novel therapeutic strategy for BRCA1‐deficient tumors is proposed: targeting GPX4‐mediated ferroptosis defense to enhance the sensitivity of Resistance to poly (ADP‐ribose) polymerase inhibitors (PARPi) and overcome tumor resistance to PARPi." (PMID 40821694, 2025).
tumor (continued). "have shown that ASP significantly downregulates the expression level of the key antioxidant factor GPX4, weakens the antioxidant capacity of tumor cells, promotes the accumulation of ROS and lipid peroxidation, and thus enhances the ferroptosis effect." (PMID 40539051, 2025). "Increased expression of IRF2, GPX4, and TIRAP, for example, has been linked to enhanced susceptibility of tumor cells to chemotherapeutic agents such as TP-3654, nelarabine, S-49076, ZM-336372, XL-147T, and tivantinib." (PMID 40535818, 2025). "In a nude mouse xenograft model, inhibiting GPX4 inhibits tumor growth and enhances Lap’s anti-tumor activity." (PMID 40191731, 2025). "It is worth noting that CD8+T cells exhibit higher sensitivity to GPX-4 inhibitors relative to tumor cells." (PMID 40169575, 2025). "In vivo, the PLNPs exhibit prolonged tumor retention, effective GPX4 knockdown, and significant tumor growth inhibition, with minimal systemic toxicity." (PMID 41220296, 2025). "In vivo tumor analysis corroborated these findings, revealing elevated expression of GPX4, GCLC, and GCLM in TIMP1-knockdown tumors." (PMID 40185230, 2025). "Malignant cells often upregulate the expression of glutathione peroxidase 4 (GPX4) during tumor progression." (PMID 41210865, 2025). "The increase in lipid peroxidation following GPX4 inhibition serves as the biological basis for ferroptosis in tumor cells." (PMID 40822852, 2025). "The mitochondrial enzyme DHODH similarly regenerates ubiquinol within the inner mitochondrial membrane, and dual inhibition of DHODH and GPX4 has been reported to induce profound ferroptosis in other tumor types." (PMID 41294853, 2025). "USP8 stabilizes GPX4 by suppressing its ubiquitination-dependent degradation, thereby attenuating ferroptosis sensitivity in tumor cells, driving tumorigenesis, and inducing resistance to PD-1/PD-L1 blockade." (PMID 40136465, 2025). "In BC, ferroptosis mediated by GPX4 inactivation can alleviate drug resistance, inhibit tumor growth, and enhance antitumor immunity." (PMID 40537877, 2025). "This interaction impacts OS prognosis, with GPX4 expression found to be negatively correlated with miR-188-3p levels, highlighting its tumor-suppressive role." (PMID 41301848, 2025). "Through comprehensive analysis, we investigated the potential relationship between GPX4 expression and tumor-infiltrating immune cells." (PMID 41142608, 2025). "In multiple tumor models, combining GPX4 inhibitors with anti–PD-1 therapy improved tumor responses and increased activated CD8+ T cell and NK cell infiltration." (PMID 40895556, 2025). "Recent preclinical studies have provided compelling evidence that pharmacological targeting of DHODH synergizes with GPX4 inhibitors, immune checkpoint blockade, or standard chemotherapeutics to enhance ferroptotic cell death and restrict tumor progression." (PMID 41369379, 2025). "To further assess the relationship between GPX4 and the tumor microenvironment (TME), we first analyzed the correlation between GPX4 expression and the levels of various immune cell infiltrates." (PMID 41142608, 2025). "Inhibiting ubiquitin-specific protease 8 can destabilize GPX4, thereby enhancing cancer cell sensitivity to ferroptosis, inhibiting tumor growth, and enhancing the efficacy of immunotherapy." (PMID 40009842, 2025). "IHC staining showed that after RGS16 was downregulated, the expression levels of Ki67 and RGS16 showed a decline, and the GPX4 protein in tumor tissues was also reduced." (PMID 40413527, 2025). "Collectively, these findings highlight PHKG2 as a regulatory “switch” that tilts tumor cells toward ferroptotic death by inactivating the NRF2/GPX4 axis." (PMID 40885710, 2025). "EETs suppress ferroptosis through a PPARγ-dependent mechanism by upregulating GPX4 levels, thereby augmenting the survival of tumor cells." (PMID 39917169, 2025).
tumor (continued). "As immunogenic cell death signals have been shown to reduce intratumoral Treg populations, further investigation into the relationship between tumor GPX4 expression, anti-PD-1/CTLA-4 treatment, anti PD-L1/other ICI regimens, and Treg function is warranted." (PMID 40001204, 2025). "Although curcumin has been reported to induce ferroptosis in various cancer types, its core signaling axis, such as the inhibition of SLC7A11/GPX4, exhibits significant variations across different tumor types." (PMID 41515171, 2025). "The results showed that the expression of NRF2, GCLM and GPX4 was increased in ESCC compared with adjacent non-tumor tissues, and the high expression of NRF2, GCLM and GPX4 was significantly associated with poor prognosis." (PMID 40707557, 2025). "GPX4 detoxifies lipid peroxides, protecting both tumor and immune cells from ferroptotic damage, whereas SLC7A11 maintains cystine uptake and glutathione biosynthesis, providing a metabolic safeguard." (PMID 41562065, 2025). "In agreement with our earlier results in DIO mice, GPX4 knockdown, as compared with scramble control, reduced tumor burden in IgG control-treated DIO mice." (PMID 40001204, 2025). "As a star protein of ferroptosis related pathway, GPX4 is related to the homeostatic imbalance of tumor immune microenvironment (TIME) of EC, thereby regulating the onset as well as progression of the cancer." (PMID 40855044, 2025). "In experiments with Treg specific deletion GPX4 mice, the addition of ferroptosis inhibitors was able to restore tumor burden." (PMID 40855044, 2025). "For example, in RSL3 target-related studies, powerful inducers such as compound 26a have been developed, which can effectively inhibit GPX4 activity and induce ferroptosis, and have shown the potential to inhibit tumor growth in mouse models." (PMID 40143112, 2025). "Accordingly, ferroptosis inducers targeting either SLC7A11 or GPX4, along with radiotherapy, can radiosensitize tumor cells by promoting ferroptosis." (PMID 40837737, 2025). "At the same time, Honokiol can reduce the expression of key antioxidant factors SLC7A11 and GPX4, further weakening the antioxidant capacity of tumor cells." (PMID 40539051, 2025). "The results indicated that macrophage depletion attenuated the tumor-suppressive effects of GPX4 knockdown." (PMID 40365295, 2025). "Its activation promotes the expression of genes involved in GSH synthesis and GPX4, thereby enhancing the antioxidant capacity of cells and establishing a positive feedback loop that maintains redox homeostasis in tumor cells." (PMID 40672941, 2025). "Single-cell RNA sequencing and spatial transcriptomics analyses further revealed tumor subpopulations within HNSCC that exhibit heterogeneous GPX4 expression, often correlating with immune exclusion and metabolic reprogramming." (PMID 40650229, 2025). "When combined with GPX4 inhibitors, icFSP1 synergistically triggers a potent ferroptotic response in tumor cells." (PMID 40862825, 2025). "The findings of this study showed that TSPO is expressed at low levels in tumor tissues, and TSPO deficiency leads to a reduction in lipid accumulation by upregulating GPX4, thereby inhibiting ferroptotic cell death." (PMID 40842566, 2025). "Cell-cell communication is also of importance in shaping the TME, where metastatic survival depends on specific signaling (through CXCL12-CXCR4) between GPX4+ tumor and NOX4+TGFB1+CXCL12+ CAFs." (PMID 41450739, 2025). "The current study demonstrated that GPX4 in tumor cells significantly regulates the tumor immune microenvironment, inducing CD8+ T cell infiltration and modulating TAM polarization towards the tumor-promoting phenotype rather than the M1 phenotype in GC." (PMID 40365295, 2025).